HRH3 (histamine receptor H3)
Description:
The H3 subclass of histamine receptors could mediate the histamine signals in CNS and peripheral nervous system. Signals through the inhibition of adenylate cyclase and displays high constitutive activity (spontaneous activity in the absence of agonist). Agonist stimulation of isoform 3 neither modified adenylate cyclase activity nor induced intracellular calcium mobilization.
Synonyms: HH3R; GPCR97
Tractability: Small molecule: an approved drug acts on it; a structure with a bound ligand is known; a high-quality ligand is known; it belongs to a druggable protein family. Antibody: its Gene Ontology location is reachable by antibodies, with high confidence; UniProt places it where antibodies can reach, with medium confidence; UniProt predicts a signal peptide or a membrane-spanning region. PROTAC: a small molecule that binds it is known.
Target class: Family A G protein-coupled receptor; Small molecule receptor (family A GPCR); Histamine receptor; Membrane receptor; Monoamine receptor
Chemical probes: CHEMBL2031737, CHEMBL555146
Gene: Protein-coding gene on chromosome 20 (62,214,960 to 62,220,303, reverse strand). Ensembl gene ENSG00000101180.
Subcellular location: Cell membrane
Pathways (Reactome):
Signal Transduction: Histamine receptors
Gene Ontology:
Molecular function: protein binding; histamine receptor activity; neurotransmitter receptor activity; G protein-coupled receptor activity
Biological process: adenylate cyclase-activating G protein-coupled receptor signaling pathway; adenylate cyclase-inhibiting G protein-coupled acetylcholine receptor signaling pathway; chemical synaptic transmission; G protein-coupled receptor signaling pathway, coupled to cyclic nucleotide second messenger; neurotransmitter secretion; G protein-coupled receptor signaling pathway
Cellular component: dendrite; plasma membrane; synapse; membrane; presynapse
Genetic constraint (gnomAD): Loss-of-function variants: 13 observed, 18.48 expected, observed/expected ratio (o/e) 0.7, 90% interval 0.46 to 1.12. The upper end of that interval is the gene's LOEUF score, 1.12, which puts it in group 4 of 6, group 1 being the genes least tolerant of losing a copy. Missense variants: 461 observed, 579.25 expected, observed/expected ratio (o/e) 0.8, 90% interval 0.74 to 0.86. Synonymous variants: 276 observed, 273.36 expected, observed/expected ratio (o/e) 1.01, 90% interval 0.91 to 1.12.
Homologues: Orthologues: chimpanzee HRH3 (99% identical), macaque HRH3 (98% identical), mouse Hrh3 (94% identical), pig HRH3 (94% identical), dog HRH3 (94% identical), rat Hrh3 (79% identical), guinea pig HRH3 (75% identical). Paralogues in human: HRH4 (35% identical), CHRM1 (25% identical), CHRM3 (24% identical), CHRM5 (24% identical), CHRM4 (23% identical), DRD3 (23% identical), DRD4 (22% identical), HRH1 (22% identical), CHRM2 (22% identical), DRD5 (21% identical), TAAR6 (20% identical), DRD1 (20% identical), and 13 more.
Diseases named in the same sentence as HRH3 in open-access papers:
HRH3 is named in the same sentence as 125 diseases in open-access papers, as found by Europe PMC text mining. Sharing a sentence is not in itself a finding about the gene and the disease. The quoted sentences say what the papers report.
schizophrenia (29 papers, 2012 to 2025). A major psychotic disorder characterized by abnormalities in the perception or expression of reality. "Taken together, these results show that CHRM3 is strongly co-expressed with GABRG2, HRH3, and CHRNA4 (risk genes for psychotic disorders, epilepsy, and schizophrenia) in THAL and other brain tissues." (PMID 31740666, 2019). "Interestingly, there are antagonists or inhibitors for the products of three DEGs that are up-regulated in isolation-reared rats and patients with schizophrenia (Snca), depression (Sod1) or both (Hrh3)." (PMID 39502833, 2024). "Indeed, several mRNAs that were differentially expressed in stressed visual cortices are recognized mediators of brain development and neurodevelopmental disorders, including Deaf1 in memory deficits and anxiety-like behaviours, Faim2 in obsessive compulsive disorder and Hrh3 in schizophrenia." (PMID 39739746, 2024).
Anxiety (20 papers, 2012 to 2026). Intense feelings of nervousness, tension, or panic often arise in response to interpersonal stresses. "Genetic inactivation of the histamine H3 receptor (Hrh3) in adult zebrafish caused reduced aggression and heightened anxiety, likely via altered serotonergic signaling in the telencephalon and hypothalamus." (PMID 35813062, 2022). "In our analyses, the HRH3 gene was found to be an important node in the calcitriol, depression and anxiety-overlapping network." (PMID 39065743, 2024). "histamine receptor h3 (hrh3) plays roles in anxiety and cognition, and recent findings suggest that this receptor could be a potential therapeutic target for ASD, but mao+/+ and mao+/− brains presented similar levels of this transcript (n=4 for each genotype; P>0.05)." (PMID 34881779, 2022). "In addition, histamine and histamine receptor H3 are expressed in the central nervous system and activate the MAPK pathway to regulate behaviors including anxiety and cognition." (PMID 38529527, 2024).
autism (10 papers, 2014 to 2025). Persistent deficits in social interaction and communication and interaction as well as a markedly restricted repertoire of activity and interest as well as repetitive patterns of behavior. "Moreover, activation of the histamine receptor H3R in the dorsal striatum was recently shown to trigger motor stereotypies in mice, and antagonism of H3R was found to attenuate elevated repetitive behavior in an animal model of autism induced by prenatal exposure to valproic acid." (PMID 30559955, 2018).
breast carcinoma (8 papers, 2014 to 2026). "Frequency distributions of HNMT, HDC and HRH3 genotypes and their associations with the risk of developing breast cancer." (PMID 24835231, 2014). "As HRH3 is a relatively small gene (5.3 kb) and rs3787429 and rs3787430 are the only 2 tag-SNPs within HRH3 according to HapMap data, it was our hope to find their associations with breast cancer." (PMID 24835231, 2014). "We found that polymorphisms of HNMT and HRH3 were irrelevant with breast cancer in the present study." (PMID 24835231, 2014). "Frequency distributions of HNMT, HDC and HRH3 alleles and their associations with the risk of developing breast cancer." (PMID 24835231, 2014). "The aim of this study is to analyze the clinical associations of polymorphisms in HDC, HNMT and HRH3 with breast cancer." (PMID 24835231, 2014). "In summary, our present study found for the first time that the variants of rs7164386 genotypes of HDC gene are significantly associated the risk of breast cancer while polymorphisms of HNMT and HRH3 might be irrelevant with breast cancer in Chinese Han populations." (PMID 24835231, 2014). "Therefore, genes that encode HDC, HNMT and HRH3 are rationally considered as candidate genes associated with development of breast cancer that is believed to be a multiple gene-related disease and whose development was previously reported to be affected by these molecules." (PMID 24835231, 2014). "However, the associations between polymorphisms of HDC, HNMT, HRH3 and susceptibility to breast cancer are still unknown so far and need to be elucidated." (PMID 24835231, 2014). "Associations between risk of breast cancer and haplotypes of two HDC variants (rs7164386 and rs7182203) and two HRH3 variants (rs3787429 and rs3787430)." (PMID 24835231, 2014). "Therefore, with respect to the notion that genetic factors contribute greatly to the risk and development of breast cancer, polymorphisms of HDC, HNMT, HRH3 and HRH4 are likely to be also associated with breast cancer risk." (PMID 24835231, 2014). "However, all the haplotypes of HRH3 were found not to be significantly associated with breast cancer risk at the corrected P level of 0.00625 (0.05/8 haplotypes)." (PMID 24835231, 2014). "However, variants of rs3787429 and rs3787430 were found not to be associated with breast cancer, which indicates that polymorphisms of HRH3 may either be minor variants for breast cancer or not affect the expression or function of HRH3." (PMID 24835231, 2014). "In our study, HRH3 expression was higher in breast cancer samples of nonobese patients than obese patients." (PMID 34566889, 2021). "Additionally, one of the histamine catabolic enzymes, histamine N-methyltransferase (HNMT), and histamine H3 (HRH3) and H4 (HRH4) receptors were also closely involved in proliferation and differentiation of breast cancer according to recent investigations." (PMID 24835231, 2014).
multiple sclerosis (6 papers, 2009 to 2018). A progressive autoimmune disorder affecting the central nervous system resulting in demyelination. "Finally, we detected high H3R expression in oligodendroglial cells from demyelination lesions in human samples of patients with MS, and validated a genetic association between an exonic single nucleotide polymorphism in HRH3 and susceptibility to multiple sclerosis." (PMID 29253893, 2017).
autism spectrum disorder (5 papers, 2020 to 2026). A spectrum of developmental disorders that includes autism, and Asperger syndrome. "Histamine dysregulation may have a role in mediating autism spectrum disorder phenotype with altered expression of key histamine signaling genes HNMT, HRH1, HRH2, and HRH3 in post-mortem brains of patients with ASD." (PMID 34335160, 2021).
psychotic disorder (5 papers, 2016 to 2024). An abnormal condition of the mind that involves a loss of contact with reality. "CHRM3 was co-expressed with three psychosis risk genes (GABAG2, CHRNA4, and HRH3) in the thalamus and other human brain tissues and mouse GABAergic neurons." (PMID 31740666, 2019).
prostate carcinoma (3 papers, 2020 to 2026). A carcinoma that arises from epithelial cells of the prostate gland. "In another hormone-dependent cancer, prostate cancer, HRH3 was found to be overexpressed in prostate cancer tissue and associated with cell proliferation." (PMID 32340124, 2020).
diabetes (2 papers, 2020 to 2022). "The results of this research may help explain the induction of tacrolimus-induced posttransplantation diabetes mellitus via the low expression of muscle genes including Tpm3, Tnnc1, Tnnt1, Tnni3, Hrh3, Apln, S1pr3, and Cxcl12." (PMID 31998808, 2020).
lung carcinoma (2 papers, 2022 to 2026). "In recent years, emerging genes have been revealed to be the potential therapeutic targets of lung cancer by inhibiting the PI3K/AKT/mTOR pathway, such as SREBP, DOK7V1, HRH3, SLFN5, and FABP5." (PMID 36349192, 2022).
basal ganglia disorder (1 paper, 2018). A disease involving the basal ganglia. "Prior work found a significant reduction in Hrh3 radioligand binding in tissue of HD patients suggesting a central role of the histaminergic system in this basal ganglia disorder." (PMID 29302618, 2018).
cervical tumors (1 paper, 2020). "In addition, the expression of two kinds of main histamine receptor (HRH1 and HRH3) in cervical tumors was measured to ascertain that apigenin did not alter the ER signal by protecting HeLa cells from receiving histamine signal." (PMID 32340124, 2020).
colonic adenocarcinomas (1 paper, 2016). "At week 18, feeding with the diets containing cimetidine (Hrh2 antagonist) and clobenpropit (Hrh3 antagonist/inverse agonist) significantly lowered the multiplicity of colonic adenocarcinoma." (PMID 26907350, 2016). "The mean MCM2-positive indices of colonic adenocarcinomas in groups 3 (p < 0.001) and 4 (p < 0.001) were significantly lower than that of group 1, indicating that dietary administration with Hrh2 and Hrh3 antagonists decreased cancer cell proliferation." (PMID 26907350, 2016).
colorectal cancer (1 paper, 2024). A primary or metastatic malignant neoplasm that affects the colon or rectum. "Inflammation-related colorectal cancer may be accelerated by Hrh2, Hrh3, and Hrh4, according to Clobenpropit, an Hrh3 antagonist and Hrh4 receptor agonist." (PMID 39070795, 2024).
endometrial cancer (1 paper, 2021). Primary or metastatic malignant neoplasm involving the endometrium (mucous membrane that lines the endometrial cavity). "The analysis showed that the expression of HRH1, HRH2, and HRH3 increased with the progression of endometrial cancer." (PMID 34768392, 2021).
endometriosis (1 paper, 2025). The growth of functional endometrial tissue in anatomic sites outside the uterine body. "Nevertheless, colocalization of HRH2 and HRH3 with CD45 was higher in this endometriosis tissue (HRH2: 0.34, 0.00–1.55; HRH3: 0.23, 0.05–0.47) than in control tissues (both 0.00, 0.00–0.00; p = 0.034 and p = 0.012, respectively)." (PMID 41516088, 2025). "In deep infiltrating endometriosis, all four receptors were present, with HRH3 exhibiting markedly elevated expression compared to controls (4.67, 2.17–8.14 vs. 0.54, 0.31–1.92; p = 0.0001)." (PMID 41516088, 2025). "The presence of HRH2- and HRH3-positive fibers within both sensory and autonomic systems in deep infiltrating endometriosis suggests that histamine may also contribute to visceral dysregulation and autonomic dysfunction, components increasingly recognized in endometriosis-associated pain syndromes." (PMID 41516088, 2025). "This pattern—reduced overall CD45-positive cell density combined with increased HRH2/HRH3 colocalization—suggests that deep infiltrating endometriosis may harbor a qualitatively distinct immune infiltrate compared with the other lesion types." (PMID 41516088, 2025). "In deep infiltrating endometriosis tissues, HRH1-, HRH2-, and HRH3-positive nerve fibers were identified in 15.63%, 52.17%, and 28.95% of nerves, respectively, whereas ovarian endometriosis showed no receptor-positive nerve fibers." (PMID 41516088, 2025). "Using gene expression data from the database provided by the University of Turku, we analyzed the expression levels of histamine receptors HRH1, HRH2, HRH3, and HRH4 across various endometriosis subtypes and control tissues." (PMID 41516088, 2025).
cancer (14 papers, 2016 to 2026). A tumor composed of atypical neoplastic, often pleomorphic cells that invade other tissues. "Mechanistically, LLNLR-299G3.1 bound to cancer-associated RNA binding proteins and regulated the expression of cancer-related genes, including OSM, TNFRSF4, HRH3, and SSTR3." (PMID 37415734, 2023). "In contrast, cleaved caspase-3 positivity in adenocarcinomas that developed in groups 3 (p < 0.001) and 4 (p < 0.001) was significantly higher than that of group 1, suggesting the induction of apoptosis by dietary Hrh2 and Hrh3 antagonists in the cancer cells." (PMID 26907350, 2016). "At the same time, inhibition of HRH3 inhibited the metastasis of HCC cells, further supporting the functional role of HRH3 in promoting the metastasis of malignant tumors, which indicates that increased HRH3 levels can be a potential prognostic marker for HCC patients." (PMID 36176778, 2022). "Next, our results showed that the expression of HRH1-HRH4, especially HRH1, HRH3 and HRH4, was dramatically upregulated in AIDS-KS tissues from two cancer patients when compared to those in normal skin tissues." (PMID 37112991, 2023). "A decrease in expression regardless of cancer grade was observed for CALM2, DRD5, ICAM1, while EGR1, HRH1, HRH2, HRH3 were overexpressed." (PMID 34768392, 2021).
tumor (7 papers, 2015 to 2024). "Histamine receptor H3 (Hrh3) inhibition reduces the tumor cell proliferation while promotes caspase-mediated apoptosis." (PMID 38730433, 2024). "The overexpression of many other amplified genes (e.g., AURKA, HRH3, MIR646, MRGBP, PCK1, PMEPA1, SLCO4A1-AS1, SOX18, TNFRSF6B) is associated with PDAC cell proliferation and tumour growth." (PMID 36289850, 2022). "We also determined whether apigenin suppressed histamine-induced tumor cell proliferation by affecting the expression of the histamine H1 (HRH1) or H3 receptor (HRH3)." (PMID 34568014, 2021). "Recent research confirmed that HRH3 was involved in tumor growth and metastasis." (PMID 35140706, 2021). "Studies have shown that HRH3 plays an important role in promoting tumor invasion and metastasis." (PMID 34566889, 2021). "In particular, most of the amplified genes are involved in proliferation and tumour progression in PDAC, such as AURKA, HRH3, MIR646, MRGBP, PCK1, PMEPA1, SLCO4A1-AS1, SOX18, and TNFRSF6B." (PMID 36289850, 2022). "Results showed that the mRNA levels of HRH1 and HRH3 were not significantly changed by apigenin treatment, indicating that apigenin did not inhibit the histamine-induced increase in tumor cell proliferation by affecting the expression of HRH1 and HRH3." (PMID 34568014, 2021).
adenocarcinoma (1 paper, 2016). A common cancer characterized by the presence of malignant glandular cells. "Adenocarcinoma cells immunohistochemically expressed Hrh1, Hrh2, Hrh3 and Hrh4 with varied intensities." (PMID 26907350, 2016).
HRH3 also shares sentences with these, for which no sentence is quoted: Alzheimer disease (31 papers); narcolepsy (31); Cognitive impairment (28); depression (15); Parkinson disease (12); neurological disorders (11); Obesity (11); epilepsy (10); neurodegenerative disease (10); attention deficit-hyperactivity disorder (7); brain disorder (7); amnesia (6); Cataplexy (6); memory impairment (6); migraine (5); psychiatric disorder (5); sleep disorder (5); allergic disease (4); cognitive decline (4); cognitive disorder (4); dementia (4); glioblastoma (4); asthma (3); cerebral malaria (3); experimental autoimmune encephalomyelitis (3); glioma (3); hepatoma (3); Huntington disease (3); infection (3); ischemia (3).
A further 76 diseases each share a sentence with HRH3 in 3 papers or fewer.